PML (PML nuclear body scaffold)
Diseases named in the same sentence as PML in open-access papers (continued):
Sharing a sentence is not in itself a finding about the gene and the disease.
tumor (continued). "Interestingly, PU.1 interacts with both RARA and PML/RARA, and while PML/RARA has been demonstrated to downregulate PU.1, ATRA treatment restores PU.1 levels, thus suggesting a tumor suppressive role of PU.1 in APL, through the transcriptional regulation of specific downstream target genes." (PMID 27626703, 2016). "However, lower expression caused by the A allele, which had a protective effect in our study, does not fit in the model of PML as a tumor suppressor." (PMID 24886876, 2014). "Moreover, this is not the only case where PML plays a role as a pro-survival protein rather than a tumor suppressor." (PMID 23936764, 2013). "In addition, high PML expression correlated with decreased survival in clear cell but not in papillary renal cancer (Fig. EV1A,B), suggesting that it may exert oncogenic functions specifically in this tumor subtype." (PMID 38730056, 2024). "Also, the formation of autophagosomes could be modulated by promyelocytic leukemia protein (PML), a tumor suppressor, localized at the MAMs by regulating the activity of the AMPK/mTOR/ULK1 pathway via affecting the transport of calcium ions from the ER to mitochondria." (PMID 34336092, 2021). "Thus, although the physiological function of PML and the nuclear bodies have not been thoroughly elucidated, their tumor-suppressive role by supporting DNA damage response pathways may be common to all of these potential functions." (PMID 29888200, 2018). "Besides, some recent researches about the mechanism of tumor-suppressor proteins, such as PML and VHL, revealed that the pathogenesis of tumors included not only the lack of some tumor-suppressor proteins and their mutation, but also their abnormal nuclear localization and rapid degradation." (PMID 28187431, 2017). "Therefore is not clear if PML-NBs really exert tumor suppressive functions or not." (PMID 23847764, 2013). "It has been observed in a number of studies that PML expression is completely or substantially lost, via unknown mechanisms, in many tumor types that are not known to be ATRX-deficient, and a more extensive survey of PML expression in cancer could potentially reveal many more." (PMID 30745338, 2019). "We did not see upregulation of reported tumour-suppressor genes, such as CDKN2A, CDKN2B and PML, and factors for neuronal differentiation, such as SMARCC1 and DLX2, in our microarray analysis." (PMID 26838672, 2016). "Moreover, PML1, rather than the well-known tumor suppressor isoform PML4, rescues the proliferation of PML knockdown cells." (PMID 38627584, 2024). "The lack of functional PML and the abnormality of ND10 have been found not only in hematologic cancers but also in the various solid tumors including breast, colorectal, prostate, lung, and bladder cancers, suggesting the critical role of ND10 in tumor suppression." (PMID 33546431, 2021). "Importantly, OTUD5 expression was significantly and positively correlated with PML levels in both tumor and nontumor tissues, supporting the supposition that OTUD5 may regulate PML in NSCLC patients." (PMID 32826889, 2020).
cancer (220 papers, 2008 to 2026). A tumor composed of atypical neoplastic, often pleomorphic cells that invade other tissues. "Here, we investigate the functional interplay of the cancer-associated DUB USP22 with the master cell fate regulatory protein PML to gain deeper insights in the pro-tumorigenic functions of USP22." (PMID 38467608, 2024). "Multivalent interactions between SUMO and SUMO-interacting motifs were observed in the formation of ALT-associated PML bodies on telomeres in cancer stem cells." (PMID 38110976, 2023). "The initial evidence revealing the association between SUMOylation and cancer derived from the identification of the promyelocytic leukemia protein (PML) and the oncogenic fusion protein PML—retinoic acid receptor-α (RARα) as SUMO substrates." (PMID 37686409, 2023). "Canonical CTNNB1 p.Ser45Pro missense mutation, as well as several other cancer-related genes (e.g., PML, HSP90AA1, BAZ1A, ARHGAP5, LHFPL6), were detected in the PT sample." (PMID 35860547, 2022). "These ALT positive cancer cells display a highly complex karyotype with excessively clustered telomeres localized in specialized PML nuclear bodies called ALT-associated PML bodies (APBs)." (PMID 33777104, 2021). "Telomeres clustered to these aggregates, mimicking the ALT associated PML-NBs found in some cancers." (PMID 34831049, 2021). "Telomere maintenance in ALT-positive cancer cells is thought to occur in ALT-associated PML bodies (APBs), specialized membraneless nuclear compartments and centers for telomere clustering." (PMID 34158486, 2021). "Loss of PML in cancer prevents the high level of Ca2+ transfer to mitochondria required for apoptosis." (PMID 32575848, 2020). "The multitasking promyelocytic leukemia (PML) protein was originally recognized as a tumor‐suppressive factor, but more recent evidence has implicated PML in tumor cell prosurvival actions and poor patient prognosis in specific cancer settings." (PMID 30927552, 2019). "Recent studies proposed that PML is implicated in the maintenance of cancer stem cells and in the promotion of anti-cancer drug resistance." (PMID 29416846, 2018). "As already pointed out, PML loss correlates with the progression of many cancers and in most cases low PML expression is associated with poor prognosis." (PMID 29888200, 2018). "Corroborating published findings in the Ubc9 knockout blastocysts, we too observed perturbation of the PML nuclear bodies and a re-distribution of the PML associated protein Daxx in cancer cell lines." (PMID 25860128, 2015). "The knowledge of precise mechanisms underlying the activation of the endogenous PML/p73/YAP axis is essential to induce the apoptosis of specific cancer cells, in addition to the DNA damage inflicted by the combination therapy." (PMID 23459691, 2013). "PIAS1 regulates PML in NSCL cancer, and it has been implicated in As2O3-mediated degradation of PML-RARα in APL." (PMID 23730625, 2013). "Results of the study showed that down-regulation of PKM2 under the effect of PML and its loss of function causes cancer." (PMID 24551779, 2012). "Earlier studies implicated Pml dysfunction in progression of a variety of cancers, and reduced or abolished expression of PML has been reported in prostate, breast, CNS, colon, lung, and gastric cancers." (PMID 22022583, 2011). "We report, for the first time, that the CSNK2A1P gene is a functional proto-oncogene in human cancers and its functional polymorphism appears to degrade PML differentially in cancer cells." (PMID 20625391, 2010).
cancer (continued). "Here, we show that PML loss increases in vitro cancer cell proliferation and migration." (PMID 37518985, 2023). "This could be attributed to the frequent loss of PML protein expression in certain cancer cells, leading to a significantly lower count of PML-NBs in the PK15 cell lines compared to primary porcine kidney cells." (PMID 37928180, 2023). "Apart from CTNNB1, we’ve identified several cancer-related gene mutations, including PML, HSP90AA1, BAZ1A, ARHGAP5, LHFPL6 in the primary tumor of HB, which may also contribute to the carcinogenesis of HB." (PMID 35860547, 2022). "PML is a well-characterized pleiotropic tumor suppressor implicated in DNA repair, apoptosis and cancer progression and is usually downregulated in many cancers including lung cancer." (PMID 33466790, 2021). "Dysregulation of PML bodies is associated with diverse cancers (Hsu and Kao, 2018)." (PMID 33138914, 2020). "Thus, in addition to PML NB-mediated nuclear retention of mTOR and inactivation of AKT, we have uncovered a novel mechanism by which PML NB loss contributes to mTOR activation in cancer via dysregulation of DDIT4 gene expression." (PMID 28332630, 2017). "This work suggests that nuclear portion of LC3 may associate with PML to control cell growth for prevention and inhibition of cancer occurrence and development." (PMID 25419843, 2014). "It is our speculation that PML deficiency might serve as a marker for cancer prediction, diagnosis, or targeting PML might become an efficient strategy for certain cancers treatment in the future." (PMID 24728382, 2014). "PML has clear suppressive function, but whether senescence loss in cancer is due to general PML decrease or only to PML IV specific loss remains an open question." (PMID 23847762, 2013). "Summary of PML modifications implicated in various human cancers." (PMID 23730625, 2013). "Finally, analysis of cancer specimens revealed that loss of PML protein expression is frequently detected in numerous human cancers." (PMID 23761861, 2013). "Therefore, our analysis suggests that PML is a putative novel regulator of class I HLAs and that PML functions to reduce the susceptibility to cancers and other diseases by controlling expression of downstream target genes, including class I HLAs." (PMID 22947142, 2012). "ALT cancer cells also contain ALT-associated promyelocytic leukaemia (PML) bodies, termed APBs." (PMID 22925423, 2012). "Since it appears that this strategy might apply to other cancers characterized by HR deficiency, it is of great interest to investigate if tumors with dysfunctional PML are susceptible to this treatment regimen." (PMID 21998700, 2011). "Furthermore, loss of PML is a hallmark of human cancers from diverse tissues." (PMID 29888200, 2018). "Further, PML degradation is regulated by post-translational modifications including ubiquitination, phosphorylation, acetylation, SUMOylation, and isomerization; and each of these pathways has been implicated in various types of cancer and offers therapeutic potential." (PMID 23730625, 2013). "The expression of promyelocytic leukemia protein (PML) is reduced in various cancers, which reduces the sensitivity to hydrogen peroxide and leads to cell death." (PMID 39979670, 2025). "Potential biomarkers of cancers with enhanced KLHL20 activity to degrade PML include increased HIF-1α and Pin1 levels." (PMID 40002221, 2025). "Neddylation of the RARα moiety in PML/RARα induces aberrant phase separation in cancer cells and enhances RARα DNA‐binding ability, which hinders the normal phase separation of this PML moiety." (PMID 40599234, 2025). "The role of tumor-suppressor protein promyelocytic leukemia (PML), also known as TRIM19, is controversial regarding the involvement with cancer progression." (PMID 40723250, 2025). "To confirm the results for the cancer cell lines, we performed IF to detect PML bodies, a marker of ALT." (PMID 40908429, 2025).
cancer (continued). "This interaction increased telomeric DNA:RNA hybrids, induced telomeric defects, and elevated ALT-associated PML bodies formation in both telomerase- and ALT-positive cancer cells in an RNAseH1 dependent manner." (PMID 41325773, 2025). "In this study, we revealed for the first time that ALKBH3-mediated m1A modification plays an inhibitory role in the formation of the PML body, which bridges our understanding of dynamic RNA modifications and phase-separation events in cancers." (PMID 38118002, 2024). "This disruption of PML-NBs leads to impaired DNA repair and increased cell survival, potentially contributing to the development of cancer." (PMID 39048945, 2024). "LLPS concerning gene fusions and mutations can also affect cancer through many pathways, such as SPOP–DAXX bodies, PML vesicles and FET fusion proteins." (PMID 39006762, 2024). "Nonetheless, some studies on human biopsies from patients further demonstrated that PML NBs are often lost during cancer progression, from various histological origins and that this loss correlates with a poor prognosis." (PMID 38611029, 2024). "For example, inhibitors of the PML-NB-associated H3K27me3 ‘writer’ EZH2, which were originally developed for the treatment of various cancers, have been found to suppress HSV, HCMV, and AdV gene expression and lytic replication in cell culture." (PMID 38399958, 2024). "SPOP–DAXX bodies, PML vesicles, and FET fusion proteins formed via multivalent interactions affect various cancers regarding gene fusion and mutation." (PMID 39006762, 2024). "Despite its predominant nuclear localization, cytoplasmic localization of PML has been reported, especially in certain cancers." (PMID 39395810, 2024). "PML is a protein at the crossroads of multiple stress responses and acts as a sensor to amplify cellular responses that participate in cancer cell clearance, notably through control of SUMO conjugation." (PMID 37382966, 2023). "PML assembles into nuclear domains that have attracted considerable attention from cell and cancer biologists." (PMID 37382966, 2023). "Collectively, PML suppresses the cancer aggressive behavior by multiple mechanisms that impede both the HIF–hypoxia–angiogenic and EMT pathways." (PMID 37518985, 2023). "This strongly suggests that PML disruption is a common factor linking glial and myeloid malignancies, uniting the PML/H3.3/IDH mutations that are common in these types of cancers." (PMID 38066546, 2023). "The authors review how PML participates in cancer cell clearance and highlight its druggable aspect." (PMID 37382966, 2023). "A first link between MAMs and cancer has been shown in case of the protein promyelocytic leukemia (PML), a nuclear tumor suppressor protein, which has been located at MERCs." (PMID 35454156, 2022). "During the last two decades, PML NBs have received strong scientific attention, and their important role in anti-viral response as well as in cell and cancer biology has been broadly documented." (PMID 36230470, 2022). "More complex pro-cancer functions of PML have been found in the maintenance of leukemia stem cells, neuroblast migration, and TNBC metastasis." (PMID 33546431, 2021). "Pin1 inhibition by small molecular compounds suppresses cancer cell proliferation and increases the protein levels of PML and SMRT." (PMID 33807199, 2021). "Our results are in line with previous findings, indicating that PML OE results in decreased proliferation rate and cell-cycle, that used different PML isoforms or biological cancer models." (PMID 34208139, 2021). "In agreement with our findings, PML has been shown to undergo proteasomal degradation in different cancers." (PMID 34625711, 2021).
cancer (continued). "One role of SUMO/SIM interactions in the function of PML nuclear bodies has been demonstrated in studies of cancer cell proliferation." (PMID 34831049, 2021). "PML, while downregulated in many types of cancer, was found to be upregulated in CML and to be a positive regulator of self-renewal in CML-initiating cells." (PMID 34316716, 2021). "The transcriptional misregulation in cancer pathway is involved in PML-RARα, which has been found responsible for the differentiation block." (PMID 33748146, 2021). "PML plays an essential role in cell cycle regulation, survival, and apoptosis, and its inactivation or downregulation is frequently observed in cancer cells." (PMID 32784588, 2020). "Paradoxically, our results indicate that, in cancer cells with high dependence on PML expression, its inhibition also triggers a senescence response that lacks canonical SASP and SAHF." (PMID 31570853, 2020). "With immunoprecipitation assay, we found YAP physically interacted with PML in ESCC KYSE-450 cancer cells." (PMID 33353561, 2020). "We proved arsenic induced degradation of PML and YAP in KYSE-150 cells, and YAP physically interacted with PML in KYSE-450 cancer cells." (PMID 33353561, 2020). "Together, these results demonstrate that upregulated Mad1 localizes to PML NBs in cultured cells and in human cancer." (PMID 30948704, 2019). "Because these PML NBs are highly characteristic of cancer cells that use ALT, they are referred to as ALT-associated PML bodies (APBs)." (PMID 30745338, 2019). "Histochemical analyses of clinical samples have shown PML to be downregulated in many cancer types such as that of breast, CNS, colon, prostate and Non-Hodgkin’s Lymphoma2." (PMID 31506431, 2019). "The RAR receptors control the homeostasis of tissue growth, modeling and regeneration, and PML-NBs are involved in self-renewal of normal and cancer stem cells, DNA damage response, senescence and stress response." (PMID 31635329, 2019). "There is a clear connection between MAMs and cancer, derived from observations on promyelocytic leukemia (PML) and Akt, a proto-oncogene frequently upregulated in tumour." (PMID 31766522, 2019). "Since circ-013226 has a low expression in CLL patients, we decided to further investigate its cancer suppress effects through miR-337-3p/ PML axis." (PMID 31152142, 2019). "The work provides a link between the Little Elongation Complex, PML bodies, and the cancer cell phenotype." (PMID 30041613, 2018). "It was first shown that ectopic expression of PML converts cancer cells from TNF-resistant to TNFα-sensitive cell death, in part by sequestering the pro-survival factor NFκB to PML NBs." (PMID 29416846, 2018). "The authors suggest a new therapeutic approach for eradication of cancer-initiating cells in leukemia through pharamacological inhibition of PML." (PMID 29888200, 2018). "A striking correlation has been observed between ALT activity in various human cancers and loss of the ATP-dependent helicase ATRX or its binding partner, the H3.3-specific histone chaperone DAXX, both of which are constituents of PML bodies." (PMID 29848986, 2018). "Several independent studies have demonstrated that overexpression of PML can slow down or block cell cycle progression in a variety of cancer cell lines." (PMID 29888200, 2018). "As nanoscopy will become less phototoxic in the future, super-resolution imaging of APBs in living cells will shed more light on the mechanisms of DNA recombination events which occur in PML NBs during telomere elongation in ALT cancer cells." (PMID 29888200, 2018). "Because C-Myc is preferentially expressed in cancer stem cells, treatment of PML-degradable agents is limited to the cancer stem cell population and not to matched non-stem cancer cells." (PMID 29416846, 2018).